IL6 (interleukin 6)
Diseases named in the same sentence as IL6 in open-access papers (continued):
Sharing a sentence is not in itself a finding about the gene and the disease.
tumor (continued). "In addition, we quantified expression of PD-L1 and PD-L2 in MM cell lines, and investigated whether cytokines present in the MM tumor environment, such as IL-6 and TGF-β1, could influence expression levels." (PMID 32922390, 2020). "Also, the levels of IL-1β and IL-6 decreased, but the level of IL-10 increased, which may reduce the cytokine-induced tumor immunosuppressive activity, cancer progression and cancer cachexia syndrome." (PMID 33013406, 2020). "This indicates that activin A may also modulate the expression of IL‐6 in human tumours." (PMID 31436048, 2020). "Moreover, EC cells produced both IL-6 and its receptor (IL-6R), thus suggesting that an autocrine/paracrine loop might cooperate in tumor progression and invasion." (PMID 32751137, 2020). "In addition, the downregulation of the proinflammatory cytokines TNFα and IL-6 in tumor tissue in rats receiving SRD supplemented with falcarinol and falcarindiol is further evidence for the anti-inflammatory action and chemopreventive effects of these dietary polyacetylenes." (PMID 32486470, 2020). "In addition to inflammatory factors such as IL-10 and GM-CSF, other factors such as tumor cell-released autophagosomes (TRAPs), long non-coding RNA HOXA transcript at the distal tip (HOTTIP), and IL-6 from cancer-associated fibroblasts (CAFs) have also been reported to regulate PD-L1 expression." (PMID 32477934, 2020). "On the other hand, tumor tissue infected with Fn exhibits an inflamed tumor microenvironment, rich in inflammatory factors such as IL6 or reactive oxygen species, leading to the assumption that Fn infection might also contribute to the generation of IAMA or L/E positive CRC." (PMID 33005238, 2020). "Through these factors, CSCs generate and activate their own tumor niche by recruiting stromal cells and modulate angiogenesis, metastasis, resistance to antitumor treatments and their own maintenance by the secretion of different factors such as IL-6, VEGF and TGF-ß." (PMID 33059744, 2020). "In addition, inhibition of IL-6 in several murine models of PDAC has limited tumor growth." (PMID 31936786, 2020). "In particular, this molecular model hypothesizes that cancer cells release large amounts of IL-6 that, in turn, determines complex chains of events (i.e., an increase in platelet count, tumor growth and metastasis) reinforcing themselves through a feed-forward loop." (PMID 31991775, 2020). "In addition, miR-21 could be packed into EVs and secreted by tumor cells in order to generate more IL-6 secretion from immune cells." (PMID 32927431, 2020). "IL-6 regulates the functional status of tumor cells mainly through two signaling pathways, namely, the Ras-dependent MAPK pathway, that may be associated with IL-6 proliferation of MM cells, and the Ras-independent STATs pathway, that may be associated with IL-6 inhibition of apoptosis in MM cells." (PMID 32293402, 2020). "Interestingly, it has been revealed that various pro-inflammatory factors such as tumor-secreted interleukin-1 and -6 (IL-1 and IL-6) mediate activation of CAFs depending on NF-κB and signal transducer and activator of transcription (STAT) transcription factors, respectively." (PMID 33158289, 2020). "Moreover, HPV-positive tumor could polarize macrophages toward classically activated phenotype (M1) and augment antitumoral IL-6 secretion." (PMID 33193693, 2020). "Many of these investigations have demonstrated the roles of IL-6 in promoting stemness by using a recombinant cytokine; others have shown autocrine sources of IL-6, or demonstrated that the cytokine was released during tumor cell interactions with other cells (such as macrophages)." (PMID 33585241, 2020). "However, if IL-6 binds to the sIL-6R, their complex can be bound to the transmembrane signal transducer protein gp130, which is ubiquitously expressed on all cell types, including tumor cells." (PMID 32867390, 2020).
tumor (continued). "Thus, it is reasonable to hypothesize that DCs infiltrating the tumor microenvironment (TME) could be stimulated to secrete TNF-α and IL-6, and are more likely to do so if they were to come in contact with EC (or tumor cells) expressing Gal-3." (PMID 33154744, 2020). "Therefore, it is speculated that increased IL-6 levels in tumor tissues may lead to the infiltration of macrophages in tumor tissues." (PMID 33224886, 2020). "Additionally, BC cells acquire an autocrine IL-6 signal that reinforces tumor growth and invasion." (PMID 32604738, 2020). "Importantly, we found that in CD68High tumors, hypoxia is associated with the expression of pro-inflammatory cytokines, such as IL1B, IL6, and TNF, previously associated with the recruitment of other anti-tumor immune cells, suggesting the establishment of a pro-inflammatory TM." (PMID 32231135, 2020). "Conversely, neutrophils can promote tumor proliferation and growth by stimulating neoangiogenesis and induce a more malignant phenotype with increased levels of mesenchymal and other tumor progression markers: such as interleukin- (IL-) 3, IL-6, nitric oxide, and arginase." (PMID 32565725, 2020). "STAT3 may be activated by cytokines such as IL-6 and IL-10 that, released by tumor cells, besides acting in an autocrine fashion to sustain cancer cell survival, may activate this pathway in myeloid immune cells in the tumor environment, resulting in an impairment of their function." (PMID 32754441, 2020). "Interestingly, propofol increased the expression of these two tumor suppressor miRNAs, which could then inhibit their target IL-6 and thus sensitize trastuzumab resistance." (PMID 32483313, 2020). "Furthermore, MSCs promote tumor cell progression via IL-6 secretion and proangiogenic factors." (PMID 32294970, 2020). "Moreover, IL‐6 induced CD4+Foxp3+ Treg migration into tumor sites by upregulating CXCR1 expression." (PMID 32931642, 2020). "In addition, the IL-6 pathway could transmit positive signals to tumor cells, promoting the proliferation, invasion and anti-apoptosis of cancer." (PMID 32655554, 2020). "The skin inflammatory process promotes skin dryness, induces infiltration of inflammatory cells, increases skin thickening and stimulates the membrane receptors of keratinocytes which promotes the release of various inflammatory mediators such as TNFα, IL-8, IL-1α, IL-6 and IL-12." (PMID 33371334, 2020). "Cancer- related pro-inflammatory cytokines, in particular IL-1 and IL-6, have been linked with the stimulation of CRP production; thus, increased CRP levels may represent an inflammatory microenvironment that supports tumor angiogenesis, proliferation, growth, and metastasization." (PMID 33023215, 2020). "However, recent studies have shown that IL-6 may play contrasting biological effects on tumor initiation depending on the types of tumor." (PMID 32134471, 2020). "While several inflammatory mediators (IL-6, TNF-α, TWEAK, TRAF6, INF-γ, and LIF) have been implicated as drivers of cancer-associated wasting, very little is known about their origin, whether skeletal muscle, immune cell, or tumor-derived." (PMID 32982782, 2020). "Furthermore, tumor cells exposed to osteoblast-derived RANKL increase their IL-6 output." (PMID 32023849, 2020). "Moreover, IL-6 has been related to tumor stage and size, metastasis, and survival." (PMID 33167343, 2020). "In addition, the further GSEA analysis in GBM patients with chemotherapy have found the enrichment of epithelial mesenchymal transition, IL6-JAK-STAT3 pathway and IL2-STAT5 pathway in high-risk group, indicating the important role of immune factors in tumor drug resistance." (PMID 31907037, 2020). "Collectively, this study suggested IL10 could inhibit the growth of the transplanted tumor in vivo and prolong survival of mice, and the primary mechanism may be the indirect inhibition of pro-inflammatory cytokines IL6 and TNF-α secretion and tumor angiogenesis formation." (PMID 32742480, 2020).
tumor (continued). "Furthermore, IL-1a secreted either by oncogene-induced senescent hepatocytes or by apoptotic hepatocytes in the DEN model can induce the production of IL-6 in KCs and trigger compensatory proliferation and tumor progression, which are essential for HCC development." (PMID 32770081, 2020). "Since IL-6 could promote the expansion and suppressive function of MDSCs, it was suggested that curcumin might inhibit the accumulation and suppressive function of MDSCs partly by reducing the level of IL-6 in tumor-bearing mice." (PMID 32005273, 2020). "Thus, the virtual NHL population satisfactorily captures and predicts clinical data on both the safety surrogate biomarker (IL6 levels) and efficacy (tumor B-cell killing) for DLBCL and is suitable for predicting the results for mosunetuzumab in a similar patient population." (PMID 32859946, 2020). "Release of sIL-6R by ADAM17 to promote IL-6 trans-signaling can be facilitated by tumor cells and macrophages, whereas ADAM17 on myeloid cells is speculated to release EGF-R ligands and activate EGF-R signaling in an autocrine manner, as well as on macrophages." (PMID 33143292, 2020). "Interestingly, in tumor-bearing mice, exercise was found to attenuate tumor growth, which correlated with increased IL-6 levels post-exercise, and systemic IL-6 blocking experiments revealed IL-6 may actually contribute to hindering tumor growth." (PMID 33329046, 2020). "Later studies have indicated that the number of tumor-infiltrating pDCs is linked with lymph node metastasis and poorer prognostic outcomes in patients with OSCC as these cells were dysfunctional with relatively low production of IFN-α, IL-6, and TNF-α as compared to circulating pDCs." (PMID 35047982, 2020). "Furthermore, TAM-derived IL-6 induces the phosphorylation of PDPK1-mediated PGK1 threonine (T) 243 in tumor cells, to facilitate a PGK1-catalyzed reaction toward glycolysis by altering substrate affinity, which upholds PDAC initiation in a metabolic regulation way." (PMID 33505964, 2020). "However, IL-6 can act also as anti-inflammatory agent interacting with TNFα and could potentially favor tumor progression." (PMID 32033013, 2020). "CHOP-deficient MDSCs displayed reduced signaling through C/EBPβ, leading to a decreased production of IL-6, and a low expression of phospho-STAT3, whereas the IL-6 expression was sufficient to rescue the immunosuppressive functions of CHOP-deficient MDSCs and restore tumor growth." (PMID 32560326, 2020). "They suggested that CAFs recruit neutrophils that then released IL-6, which could induce neutrophil activation and PD-L1 expression; thus, the PD-L1+ activated neutrophils have a pro-tumor role through the IL6-STAT3-PD-L1 signaling pathway to inhibit T cell immunity." (PMID 32359357, 2020). "In addition, the systemic elevation of some cytokines, such as TNFα, IL-6, IL-8, and IL-10, observed in GD patients, which are known to promote tumor development, could be involved in the increased tumor growth we observed." (PMID 32085512, 2020). "IL-6 rises great attention in oncology, since trans-signaling due to soluble form of the IL-6 receptor not only accounts for more recurrent inflammation, but also enhances chemotherapy-resistance, tumor growth, metastasization and epithelial to mesenchymal transition." (PMID 32468851, 2020). "Thus, the role of the IL-6 trans-signaling in the context of cancer might be dependent on many factors of the tumor microenvironment, such as cell type, tumor location or severity of cancer." (PMID 32370100, 2020). "Though IL-6 also drives tumor growth and promotes survival of neoplastic cells, these tumor-promoting activities are completely counteracted by the effect of T lymphocyte infiltration into the tumor site with a result of tumor cell killing and tumor regression." (PMID 33240283, 2020).
tumor (continued). "In addition, the number of IL-6- and IL-8-positive tumour cells positively correlated with other advanced-stage clinical characteristics, including tumour invasion, lymphoid node and distant metastases and tumour size." (PMID 31324197, 2019). "A close direct correlation was noted between preoperative IL-6 levels and themaximal dimension of cardiac myxoma or tumor volume.No significant correlationships were found between ∆IL-6 and maximaldimension of tumor (r=0.0424, P=0.4480) or tumor volume(r=0.0574, P=0.4297)." (PMID 30810670, 2019). "Further, conditioned medium from MSCs exposed to tumor cell-derived extracellular vesicles (EVs) caused an upregulation in STAT3 phosphorylation and proliferation of CCA cells, possibly by secretion of CCL2/MCP1, CXCL1/GRO-α, CXC3CL1/Fractalkine, IL-6, and PDGF-AA." (PMID 31921870, 2019). "In addition, systematic administration of IL-6/IL-6R antagonist(s) with MCT-1 inhibitor(s) may promote immune cell infiltration to advance therapeutics against tumor heterogeneity and aggressiveness, with fewer adverse effect(s)." (PMID 30885232, 2019). "Moreover, previous studies have indicated that tumor-derived interleukin-6 could stimulate thrombopoiesis, leading to thrombocytosis and tumor progression in patients with ovarian cancer." (PMID 31375109, 2019). "Finally, whether in patients with maximum tumor size ≤ 5 cm or >5 cm, high preoperative serum IL6, IL8, and TNF-α levels were distinctly correlated with shorter RFS." (PMID 31781194, 2019). "The IL-6 secretory phenotype of ADSCs co-cultured with cancer cells has been observed in many studies and is accompanied by elevated cancer cell proliferation and metastasis, which suggests a role for ADSCs in promoting tumour proliferation and invasive properties." (PMID 31196220, 2019). "To further determine whether human TRAPs (hTRAPs) could induce human CD4+ T cells to produce IL-6, we collected hTRAPs from the culture media of 3 human tumor cell lines, A375, MDA-MB-231 and HepG2, and from the malignant effusions or ascites of 8 cancer patients." (PMID 31300052, 2019). "Furthermore, concentrations of IL-6 and IL-8 were also correlated with tumor burden." (PMID 31781510, 2019). "IL-6 role has been widely investigated in different types of human neoplasia and the studies showed that it may act in an autocrine or paracrine manner, influence the growth of a tumor either directly or indirectly, through modification of tumor environment." (PMID 31342143, 2019). "Furthermore, matrix metalloproteinases composing the SASP promote migration of cancer cells while SASP IL-6 and IL-8, in addition to promoting tumor growth, have been reported to induce an epithelial to mesenchymal transition, thereby stimulating invasion and cancer stemness reprogramming." (PMID 31186408, 2019). "As a tumor is often described as being like a “chronic wound”, the hypoxic conditions and high concentration of cytokines and growth factors IL-1α, IL-1β, IL-6, FGF-2, IGF-1, TGF-β, VEGF-A, HIF-1α, EGF, TGF-α are a likely trigger for MSCs recruitment to tumor microenvironments." (PMID 31569731, 2019). "Moreover, intratumor IL-6 production both by tumor cells and TILs, detected by IHC, may serve as a likely source of salivary IL-6 mRNA and protein in patients with OSCC." (PMID 31766212, 2019). "The production of IL-6 is mainly associated with NF-κB activation and the involvement of IL-6 in CRC progression is actually accepted; indeed, a recent study demonstrated the direct correlation between IL-6 levels and Tumor Node Metastasis (TNM) stage and with less histological differentiation." (PMID 31191652, 2019). "These adipocytes located near the tumor are called “cancer-associated adipocytes” (CAA) and are characterized by a loss of lipid content, a decrease in late marker expression of adipogenesis, and an overexpression of inflammation markers (IL-6, IL-1β) and proteases (MMP-11, PAI-1)." (PMID 31756890, 2019).
tumor (continued). "Simultaneous hypermethylation of multiple tumor suppressor gene promoters by IL-6-mediated signaling leads to epigenetic silencing of tumor suppressor gene expression, suggesting that it may be an important mechanism contributing to chronic inflammation-induced cancer in the oral cavity." (PMID 31557902, 2019). "Furthermore, it has been shown that the transfected 4T1 tumor cells constitutively expressing IL-6 induced expansion of MDSCs and restored MDSCs accumulation in tumor-bearing IL-1 receptor knockout mouse, suggesting that IL-6 is likely to be a relevant IL-1β downstream mediator." (PMID 30998767, 2019). "Finally, Cyr61 may be involved in the process of tumor metastasis and progression by producing IL-6 and CRP in the EOC inflammatory microenvironment." (PMID 31766991, 2019). "Mast cells may promote inflammation, inhibition of tumor cell growth, and tumor cell apoptosis by releasing cytokines, such as IL-1, IL-4, IL-6, IL-8, monocyte chemotactic protein-3 and -4 (MCP-3 and MCP-4), transforming growth factor beta (TGF-β), and chymase." (PMID 30678047, 2019). "This suggests different regulatory mechanisms may be applicable between TIMP-1 and IL-6 expression depending upon elements present within various cell types or cancer specific tumor microenvironments, and our results may be specific to this interaction within NSCLC." (PMID 31443242, 2019). "The exact, probably tumor-derived, factors that initiate this inflammatory transition remain to be elucidated, but this inflammatory state has been shown to be perpetuated by pro-inflammatory cytokines (IL-6, LIF) through both STAT3 and STAT4 dependent mechanisms." (PMID 31731701, 2019). "Notably, the upregulation of IL-6 in human HCC was shown to induce tumor development." (PMID 31340754, 2019). "Importantly, targeting some of these mechanisms, such as the CXCL12-CXCR4 and IL-6 pathways, could result in inhibition of both the tumour stroma and the tumour itself." (PMID 31308358, 2019). "Some studies demonstrated that IL-6 could promote tumor growth." (PMID 30805774, 2019). "Platinum compounds may also trigger the ability of tumor cells to shape the immunosuppressive microenvironment, such as inducing M2 polarization of macrophages through the IL-6/STAT3 and NF-κB pathways; these changes indirectly contribute to the chemoresistance of cervical and ovarian cancers." (PMID 30927928, 2019). "Moreover, in i.v. animal model, the cells with Ki-67 positive in the tumor regions from the IL-6-treated group (inoculated by SPC-A-1) were increased when compared with those from other groups, including SPC-A-1 alone, BGC-823 alone, and the respective hUCMSCs or hAMSCs co-injection groups." (PMID 30805774, 2019). "Because various types of tumors produce several cytokines (IL-6, IL-8, TNFα) and growth factors (G-CSF), which are known to stimulate the activity of neutrophils, we aimed to investigate the influence of tumor-derived G-CSF on NET formation by the neutrophils isolated from the blood of HNC patients." (PMID 31438586, 2019). "Moreover, IL-6 from TTRAP remarkably suppressed T cell anti-tumor effector function." (PMID 31300052, 2019). "Remarkably, compared to intact TRAPs, tumor cell lysates containing an equal amount of total protein but much more Hsp90α, or sonicated TRAPs containing an equal amount of Hsp90α, or proteinase K-treated TRAPs were much less effective in inducing IL-6 secretion from CD4+ T cells." (PMID 31300052, 2019). "The results of our study also show possible moderators of the reduction in IL-6 include the type of tumor removal surgery (less invasive surgery), as well as changes in both weight and pain (the greater the reduction of these factors, the greater the reduction of IL-6)." (PMID 31414667, 2019). "Interestingly, stimulation of mouse neutrophils with IL-6 and G-CSF induced a tumor-promoting N2 phenotype, characterized by TRAIL down-regulation, but TRAIL expression could be rescued by IFNγ or TNF." (PMID 31574961, 2019).